PIK3CA (phosphatidylinositol-4,5-bisphosphate 3-kinase catalytic subunit alpha)
Diseases named in the same sentence as PIK3CA in open-access papers (continued):
Sharing a sentence is not in itself a finding about the gene and the disease.
tumor (continued). "Isoform-specific targeting of PIK3CA by small molecule inhibitors or siRNA can significantly block tumor growth and induce apoptosis in human cancer cells." (PMID 18335034, 2008). "This “physiologic” level of PIK3CA expression serves as an intracellular mediator maintaining tumor cell proliferation and growth by responding to extracellular growth factors." (PMID 18335034, 2008). "PIK3CA mRNA levels were significantly higher in invasive carcinomas compared with benign and low malignant potential neoplasms." (PMID 19384426, 2007). "In human cancer, recent reports have described activating mutations in the PIK3CA gene encoding p110α, and inactivating mutations in the phosphatase and tensin homologue (PTEN) gene, a tumour suppressor and antagonist of the PI3K pathway." (PMID 19384426, 2007). "From their study of 33 MSI and 201 microsatellite stable (MSS) CRC cases, PIK3CA mutation was present in 48% of the MSI tumours, but only in 29% of the MSS tumours." (PMID 15784156, 2005). "It effectively reduced the growth of human tumor xenografts in vivo, including those harboring PIK3CA GoF variants, without impact on blood glucose levels." (PMID 41272322, 2026). "Additionally, high anoikis risk scores were associated with increased mutations frequencies of PTEN, PIK3CA and ZEB2, along with lower tumour mutation burden, microsatellite instability and PD-L1 levels." (PMID 42258564, 2026). "In the EP group, 12 tumours had pathogenic mutations in key genes associated with response to anti‐EGFR therapy (1 × in BRAF + PTEN, 1 × in BRAF + PIK3CA, 2 × in BRAF, 3 × in PTEN, 2 × in NRAS, 1 × in KRAS, 1 × in HRAS and 1 × in PIK3CA)." (PMID 40302146, 2025). "PIK3CA CN gain is reported to occur preferentially in PIK3CA mutant tumours potentially leading to more aggressive disease and a different response to treatment with supporting the hypothesis of a potential additive effect of mutations and gain to oncogenesis." (PMID 41351070, 2025). "Our findings highlight a novel correlation between PIK3CA mutations and Pb exposure in CRC, suggesting that environmental heavy metals may interact with oncogenic signaling pathways to shape tumor heterogeneity." (PMID 40687430, 2025). "In an in vivo experiment using engineered mice harboring ARID1A loss and PIK3CA mutations, treatment with the PIK3 inhibitor buparlisib led to a dose-dependent reduction in AKT levels and tumor viability, highlighting the therapeutic potential of buparlisib in OCCC with these co-mutations." (PMID 41514650, 2025). "Targeted second-line therapies for HR+/HER2-mBC include alpelisib in patients with activating mutations in tumor PIK3CA, which significantly improved PFS in patients with PIK3CA mutations who received alpelisib plus fulvestrant compared to placebo plus fulvestrant." (PMID 40344957, 2025). "Capivasertib is known to have antitumor activity against PIK3CA/AKT-mutated tumors, and therefore we tested whether this drug would enhance the efficacy of CAR T cell therapy in the context of tumor-bearing PIK3CA/AKT pathway mutations." (PMID 40008088, 2025).
tumor (continued). "The retrospective design and the treatment period also precluded the collection of data on relevant tumor genomic alterations, such as PIK3CA, AKT, PTEN, and ESR1, which limited our ability to assess the potential association between these tumor mutations and treatment outcomes." (PMID 39982725, 2025). "Although we did not examine concordance of results in the liquid versus the tissue biopsy cohort for alterations in genes other than PIK3CA, PTEN, AKT1, AKT2, and AKT3, our results support the value of blood-based NGS panel testing in providing a comprehensive tumor mutational landscape." (PMID 40597213, 2025). "Mutations in the PIK3CA gene or loss of PTEN function are common causes of dysregulation in this pathway in cancer, leading to increased cell survival and proliferation, which contributes to tumor progression and resistance to treatment." (PMID 40143209, 2025). "This relationship is significant because it suggests that ARID1A mutations may cooperate with other genetic mutations, such as PIK3CA or PTEN loss, to promote aggressive tumor behavior." (PMID 40072110, 2025). "When evaluating non-clonal tumor pairs, we observed two non-clonal tumors with an identical PIK3CA mutation which is reported to have a prevalence of 2.8% among LUSC tumors from The Cancer Genome Atlas." (PMID 40373350, 2025). "For the SOLAR-1 and SANDPIPER trials, which did not report complete PFS data, we derived the results by synthesizing PFS data from patients with and without PIK3CA mutations confirmed through tumor tissue testing." (PMID 40535135, 2025). "The third NGS analysis of tumor-normal DNA from a progressive bone biopsy taken under Infigratinib treatment revealed a different somatic single nucleotide variant (SNV) profile with an oncogenic, activating PIK3CA c.3140A>T, p.(His1047Leu) variant." (PMID 40260297, 2025). "Preclinical studies have shown that it can induce sustained tumor regression in PIK3CA mutant tumor xenograft models without causing metabolic disorders." (PMID 40723456, 2025). "The lack of molecular data (e.g., PIK3CA mutation) restricted the ability to explore biological differences in greater depth, particularly in relation to treatment resistance and tumor biology." (PMID 40620732, 2025). "Our data support the role of ctDNA in capturing ongoing tumor evolution, suggesting that specific mutations, including rare variants in KRAS, EGFR, and PIK3CA, may contribute to resistance and progression." (PMID 40652269, 2025). "Our findings suggest the clinical utility of liquid biopsy in capturing tumor-derived genetic alterations and indicate that PIK3CA mutations are not uniformly distributed across subtypes, nor do they confer identical prognostic implications." (PMID 41415546, 2025). "miR-203a can also act as a tumor suppressor through directly interacting with PIK3CA." (PMID 40142329, 2025). "Compound 52 showed a reduction in tumor volume in PIK3CA mutant SKOV3 xenograft models." (PMID 38584538, 2025).
tumor (continued). "In addition to CCND1, rearrangements involving genes such as PIK3CA and EGFR are also implicated in OSCC pathophysiology, contributing to tumor progression and reduced therapeutic efficacy, thereby representing potential targets for novel treatment strategies." (PMID 40427514, 2025). "This distinction underscores the complexity of mTOR pathway regulation in UCS and indicates that TSC2 and PIK3CA may exert their effects on tumor biology via divergent mechanisms." (PMID 41181577, 2025). "Overall positive percent agreement (PPA) for short variants across ctDNA tumor fraction (TF) subgroups in paired biopsy samples was: ctDNA TF ≥ 10%: PIK3CA, 93.9%; AKT1, 100%; PTEN, 100%; ctDNA TF 1%-10%: PIK3CA, 96.3%; AKT1, 100%; PTEN, 100%; ctDNA TF < 1%: PIK3CA, 34.7%; AKT1, 50.0%; PTEN, 37.5%." (PMID 40597213, 2025). "The results demonstrated widespread PIK3CA expression across various tumor types." (PMID 40723456, 2025). "Although these mutations were detected less frequently in comparison to PTEN and PIK3CA mutations, the detection rate of PIK3R1 mutations was similar in both tumor and cfDNA samples (only a 0.8% difference), which implies that these mutations can be reliably detected when present in GBM patients." (PMID 40564017, 2025). "Moreover, the combination of CB-839 and 5-fluorouracil (5-FU) induces PIK3CA-mutant tumor regression in xenograft models." (PMID 39717717, 2025). "Tumor and metastatic tissues exhibited higher PIK3CA expression compared to normal tissues." (PMID 41009348, 2025). "PIK3CA, an oncogene involved in the PI3K/AKT signaling pathway, promotes the dedifferentiation of mammary cells into a plastic stem‐like state during the early stages of tumor initiation through its gain‐of‐function mutations." (PMID 41415713, 2025). "In contrast, CS and PIK3CA expression were reduced in the tumor tissues (P < .01)." (PMID 40696656, 2025). "On the other hand, a higher presence of CD3+, CD8+, PD-1+, tumor infiltrating lymphocytes (TILs) and high mutational tumor burden (TMB) are associated with a better survival while PIK3CA mutations have been associated with worse survival in ASCC irrespective of p16 status." (PMID 40336180, 2025). "Hence, it remains possible that mTOR inhibition or more specific PIK3CA inhibition would have been able to resensitize the tumor of the presented patient to Infigratinib treatment." (PMID 40260297, 2025).
tumor (continued). "Based on our discovery of a dominant underlying mechanism of OT resistance in our xenograft RMS models, we also credentialled PIK3CA/AKT pathway inhibition as a preclinical therapy that re-sensitizes RMS to chemotherapy-induced tumor cell killing by co-treating them with alpelisib PIK3CA inhibitor." (PMID 41372143, 2025). "The aim of this study was to quantify the expression levels of the immune checkpoint molecules TIM-3 and Gal-9 in CRC tissues and adjacent non-tumor tissue, and to investigate their associations with key oncogenic mutations, including KRAS, NRAS, BRAF, PIK3CA, and AKT1, as well as MSI status." (PMID 40724985, 2025). "RLY-2608 elicited objective tumor responses in two patients diagnosed with advanced hormone receptor-positive breast cancer with kinase or helical domain PIK3CA mutations, with no observed WT PI3Kα-related toxicities." (PMID 40723456, 2025). "In addition, the data suggest that further consideration of the PTEN protein status of PIK3CA altered ER+ BC tumours is warranted to understand how this modulates response to treatment." (PMID 40263319, 2025). "Notably, while preoperative PIK3CA positivity indicated more advanced tumour staging, postoperative PIK3CA positivity predicted better prognosis." (PMID 40817602, 2025). "For the SOLAR-1 and SANDPIPER trials, which did not report PFS for the overall population, we estimated PFS by integrating data from patients with and without PIK3CA mutations identified in tumor tissue." (PMID 40535135, 2025). "Additionally, cyclin D1 (CCND1; chr 11q), fibroblast growth factor receptor 3 (FGFR3; chr 4p), and PIK3CA (chr 3q) were amplified in the tumor tissues from patients S390 and S425, S425 and S028, and S425 and S424, respectively." (PMID 41301905, 2025). "Finally, Phosphatidylinositol-4,5-bisphosphate 3-kinase catalytic subunit alpha (PIK3CA) (PDB ID: 7R9V) is a catalytic subunit of PI3K and is frequently mutated in breast cancer, driving tumour progression through enhanced signalling activity." (PMID 40430480, 2025). "Furthermore, when treating mice with the ICI Nivolumab (αPD-1), we found that the efficacy of Nivolumab in inhibiting tumor growth was markedly lower in the PIK3CA-mutant group compared to the wild-type group." (PMID 40328748, 2025). "For instance, about 20–30% of HPV(+) HNSCC have mutations in PIK3CA; detecting a PIK3CA mutation in plasma ctDNA alongside HPV16 might indicate a high tumor fraction and possibly identify a targetable pathway (PI3K inhibitors)." (PMID 41226995, 2025). "While co-mutations of FGFR2 with PIK3CA or truncating exon 18 FGFR2 variants occur in other tumor types, these have not previously been reported in sialoblastoma." (PMID 40906279, 2025). "Assays typically survey driver mutations relevant to lung cancer biology and therapy resistance – such as KRAS, PIK3CA and EGFR – and clonal‐haematopoiesis (CH) genes like DNMT3A and TET2, which are monitored to distinguish tumour DNA from age‐related background variants." (PMID 40847555, 2025). "Treatment based on molecular findings (PIK3CA mutation), genetic findings (BRCA1/2 germline mutation), or adapted to the change in the tumor phenotype in rebiopsy (anti-HER2 therapy in the transformation to HER-2-positive disease) was grouped into tailored treatment." (PMID 38912058, 2024).
tumor (continued). "Therefore, the observed associations between the expressions of the SEMA7A, SEMA4D, ADAM8, and ADAMTS10 in tumor groups with KRAS, NRAS, BRAF, PIK3CA, and AKT mutations require validation in larger study cohorts." (PMID 39329961, 2024). "We also detect mutations in MET, which codes for proteins involved in cell growth and survival; PTEN, which is involved in the tumor immune microenvironment; and PIK3CA, which is involved in the tumor immune microenvironment, at 33.33% and 30.30%, respectively." (PMID 39759612, 2024). "The dynamic changes observed in key mutations such as BRAF, APC, GNAS, EGFR, and PIK3CA suggest that ctDNA analysis can offer unique insights into tumor evolution that are not captured by traditional tissue biopsies." (PMID 39796090, 2024). "Tumor heterogeneity is one of the most significant obstacles to PIK3CA-based therapy." (PMID 39369580, 2024). "Among the major mutations, the PIK3CA mutation-positive group had significantly higher TPS than the wild-type group, but not CPS, showing a potential association between PIK3CA mutation and tumor-intrinsic PD-L1 expression." (PMID 39136017, 2024). "Genetic testing revealed no mutations in common oncogenes, such as KRAS, BRAF, or PIK3CA, supporting the borderline nature of the tumor." (PMID 39816315, 2024). "The non-PIK3CA mutations were HPV type and tumor histology dependent." (PMID 39266536, 2024). "Tumor regression exclusively in mice bearing the PIK3CA mutation, whereas those with wild-type PIK3CA did not respond to the treatment." (PMID 39066355, 2024). "Targeted NGS analyses of the tumor and PDC both identified a PIK3CA M1004I mutation and an EGFR 19 deletion, which together may have caused the resistance to erlotinib." (PMID 38398169, 2024). "And its efficacy can vary depending on genetic mutations within the tumor, such as KRAS and PIK3CA mutations, which may influence resistance to certain drugs." (PMID 39555098, 2024). "We first performed RNA-Seq on isogenic DLD1 PIK3CA WT-only and Mut-only cell lines treated with either vehicle or the combination of CB-839 and 5-FU, because the drug combination induced more NETs and tumor-infiltrating neutrophils in PIK3CA-Mut–only tumors than the isogenic WT-only tumors." (PMID 38194275, 2024). "Our data revealed that the PIK3CA of the tumours in low-DR group may have a higher probability of harmful mutations that make cancer cells less responsive to DR." (PMID 38507875, 2024). "When these tumors were grown in CDXs, they observed that tumor growth could be attenuated in the tumors that harbor amplification of PIK3CA (PI3K gene) by antagonizing GLI1 and PI3K, further supporting their regulatory function." (PMID 39796653, 2024). "However, the PIK3CA-mutant tumors had more tumor-infiltrating neutrophils than tumors of the parental counterparts." (PMID 38194275, 2024). "Another mechanism of sensitivity to immune checkpoint inhibitors caused by PIK3CA gene mutations is that they can increase the TMB, resulting in more neoantigens and enhancing the immunogenicity of the tumor to increase sensitivity to immune checkpoint inhibitors." (PMID 39555098, 2024). "In this review, we focus on the PIK3CA gene and its role in tumor tropism." (PMID 39369580, 2024).